RNU6-318P (RNA, U6 small nuclear 318, pseudogene)
Synonyms: RNU6-1295P
Gene: Small nuclear RNA gene on chromosome 12 (12,289,227 to 12,289,329, reverse strand). Ensembl gene ENSG00000207010.
Homologues: Orthologues: chimpanzee U6 (98% identical), chimpanzee U6 (95% identical), pig U6 (85% identical), dog U6 (82% identical). Paralogues in human: RNU6-74P (89% identical), RNU6-1 (88% identical), RNU6-116P (88% identical), RNU6-15P (88% identical), RNU6-2 (88% identical), RNU6-393P (88% identical), RNU6-3P (88% identical), RNU6-4P (88% identical), RNU6-5P (88% identical), RNU6-6P (88% identical), RNU6-9 (88% identical), RNU6-10P (87% identical), and 1285 more.